NRAS (NRAS proto-oncogene, GTPase)
Diseases named in the same sentence as NRAS in open-access papers (continued):
Sharing a sentence is not in itself a finding about the gene and the disease.
tumor (continued). "More importantly, we show that CXCR1/2‐mediated pneumotropism can be annihilated, since navarixin significantly prevented lung tumor colonies sprouted by circulating NRAS‐mutant tumor cells." (PMID 28341702, 2017). "Second, mutant NRAS was required for spontaneous homing to the lungs of two cancer cell lines and NRAS mutation and/or overexpression was sufficient to transmit this phenotype to NRAS‐wild‐type tumor cells, as well as to benign cells." (PMID 28341702, 2017). "CD3+ T cell infiltration of the tumor correlated with good response, whereas the presence of a BRAF or NRAS mutation correlated with poor response, especially in patients pretreated with a BRAF inhibitor." (PMID 29157311, 2017). "Of these, four KRAS mutations, two NRAS mutations, two histone H3 mutations, and one ALK mutation were predicted to encode epitopes in at least one tumor." (PMID 28854978, 2017). "Activating mutations of the oncogenes BRAF and NRAS lead to constitutive signaling of the mitogen-activated protein kinase (MAPK) pathway and thereby enhance tumor growth and promote disease progression." (PMID 28797232, 2017). "Usp9x, Ets-1 and NRAS protein expression was further assessed in a tissue microarray containing tumour and normal tissue." (PMID 28198367, 2017). "Future studies will examine how RhoJ cooperates with other MAPK drivers, such as NRAS, to promote tumor growth." (PMID 28753606, 2017). "Our evidence suggests that these receptors also directly impact metastasis, as we found that they are required to fine‐tune the sustained lodging and outgrowth of NRAS‐mutant circulating tumor cells in the lungs." (PMID 28341702, 2017). "Only three patients had KRAS, NRAS or BRAF mutations, which we were able to follow in cfDNA and BM-derived tumour DNA during the course of trametinib therapy to evaluate the subclonal response to treatment." (PMID 28492226, 2017). "Regarding the NRAS gene, some rare variations in codons 12, 13, 61, 117, and 146 (exons 2–4) have been related to intrinsic tumor resistance and worse ORR, PFS, and OS, recommending pre-treatment, and possibly post-treatment, genotyping." (PMID 28708103, 2017). "Further, overexpression of NRAS induced the migration of GSCs in a 3D Spheroid-based tumor migration assay." (PMID 27556696, 2016). "Provided the relatively low incidence of the single gene mutations, clonal mutations (detected in >20% of tumor population) were grouped into the JAK/STAT (IL7R, JAK2, JAK1, CRLF2 mutations and CRLF2-rearrangements) and RAS/RTK (FLT3, KRAS, NRAS) pathways." (PMID 26883104, 2016). "Single cell clone sequencing from the cell culture generated from this treatment resistant tumor revealed the co-occurrence of a BRAF and NRAS mutation in a single cell." (PMID 27791198, 2016). "Somatic mutations in these genes were detected in 537 of 1284 (41.8 %) primary tumours: 457 (35.6 %) KRAS, 53 (4.1 %) NRAS, and 27 (2.1 %) BRAF mutations." (PMID 27737711, 2016). "By tNGS primary tumours were RAS wildtype in 5/14 and mutated in 9/14 (8/9 KRAS exon 2; 1/9 NRAS Exon 3) of cases." (PMID 27756406, 2016). "We detected an extraordinary level of tumor heterogeneity, with microclonal (mutant allele fraction <0.10) KRAS, NRAS, FLT3, and/or PTPN11 hotspot mutations evident in 31/57 (54.4%) patients." (PMID 27683039, 2016). "HRAS was down-regulated in neighbouring and tumour tissue compared to the normal mucosa, while NRAS seemed to be equally down-regulated in neighbouring and up-regulated in tumour tissue." (PMID 27465361, 2016). "Extended mutation analyses of additional tumour RAS loci (KRAS exons 3 and 4, and NRAS exons 2, 3 and 4) suggested that the efficacy benefit was further restricted to patients with tumours wild type at all screened loci." (PMID 26766738, 2016).
tumor (continued). "One recent study found that using a combination of an antibody-drug conjugate targeting EDNRB, together with small-molecule inhibitors of the MAP kinase pathway, increased anti-tumor activity in BRAF/NRAS mutant cell lines and tumor models." (PMID 27148356, 2016). "Data were analysed by tumour RAS (KRAS/NRAS) and BRAF status, and baseline amphiregulin (AREG) expression." (PMID 27764839, 2016). "KRAS, NRAS and BRAF mutations were detected in two or all three tumor types while mutations in EGFR were uniquely detected in NSCLC." (PMID 27101000, 2016). "Multiregion analysis was performed in 60 spatially separated tumor areas according to the pathological tumor node metastasis (pTNM) staging and KRAS, NRAS and BRAF mutations were tested using pyrosequencing." (PMID 27916952, 2016). "NRAS and BRAF mutations have been reported traditionally to be nearly mutually exclusive in a single tumor with nevertheless rare exceptions of double mutants." (PMID 26204954, 2015). "One sarcomatoid tumor sample harbored four mutations in the EGFR, MEK1, NRAS, and PTEN genes, respectively." (PMID 25470237, 2015). "Western blot analysis revealed minimal differences in MAPK activity in NRAS versus NRAS-ΔPTEN tumours, whereas the status of the PI3K/PTEN/AKT signalling pathway was significantly different for the two genotypes." (PMID 26307673, 2015). "Mutations in these genes were almost exclusively identified in BRAF/KRAS/NRAS mutant tumours, suggestive of cooperative biological effects." (PMID 26506417, 2015). "As established in previous studies, majority of tumor cell lines possess a mutation in either KRAS, NRAS or BRAF genes was sensitive to AZD6244 in vitro (IC50 < 1 μM)." (PMID 26567773, 2015). "Molecular analysis of NRAS and NRAS-ΔPTEN tumours was performed to evaluate the level of β-catenin, PTEN, CAV1 and the cell–cell adhesion molecule and β-catenin interactor, E-cadherin (ECAD)." (PMID 26307673, 2015). "To assess the role of hnRNP K in the DNA damage response with respect to MAPK signaling activity in MM, we used NRAS-mutant IPC-298 MM cells as an in vitro tumor model." (PMID 26136337, 2015). "In most tumour types exhibiting mutation of a RAS gene family member (HRAS, KRAS, or NRAS), the mutational activation of one member predominates." (PMID 25361007, 2014). "The mutational status of NRAS, member of the MAPK pathway, showed stability over multiple different tumor sites and over a span of 8 years between original diagnosis with SBT and recurrence with an invasive LGSC (case LGSC-9)." (PMID 25523272, 2014). "In general, the mutual exclusivity of mutations of NRAS and KRAS in varied tumor types suggests that they provide similar or identical oncogenic signals." (PMID 25361007, 2014). "Analysis of plasma from 4 patients identified mutations identical to those found in tumor specimens (BRAF, NRAS, TERT)." (PMID 25516806, 2014). "One patient had a primary tumor that was NRAS wild type and BRAF mutant and stained homogeneously positive with VE1." (PMID 25526463, 2014). "As already reported for these neoplasms, BPDCN also shows a clear predominance of NRAS mutations over KRAS mutations." (PMID 25115387, 2014). "Of interest, most NRAS (5 of 6) and all BRAF (3 of 3) mutations clustered in ICC tumour subtype and were mutually exclusive with KRAS (15.7%)." (PMID 24867389, 2014). "MEL9 is characterized by both NRAS and BRAF mutations in founding clone, along with a CTNNB1 P16S mutation that arose later in the evolution of the tumor." (PMID 25393105, 2014).
tumor (continued). "Among the AGC patients whose tumor tissue contained gene mutations, multiple mutations of KRAS codon 13, PIK3CA codon 545 and NRAS codon 12 were detected in only one case." (PMID 24774510, 2014). "Our findings confirm that genetic alterations that occur early in colorectal carcinogenesis, namely mutations in APC, KRAS, NRAS, and BRAF, persist through tumor evolution and show an exceedingly high level of concordance between primary tumor and metastases." (PMID 25164765, 2014). "In tumors three and four, there was a distinct somatic mutation in MTOR (categories 2 and 3, respectively) in each tumor, and PBRM1 and KDM6A and NRAS mutations (all category 3) in tumor three." (PMID 25159823, 2014). "The receptor tyrosine kinases EGFR and ERBB2, the GTPases KRAS, NRAS, and HRAS, and the kinase BRAF are frequently mutated in cancers and can drive tumor proliferation." (PMID 24874471, 2014). "We collected formalin-fixed, paraffin-embedded and fresh frozen tumor samples from AGC patients and analyzed the KRAS, NRAS, BRAF and PIK3CA mutations by direct-sequencing." (PMID 24774510, 2014). "The median ages of patients whose tumor tissue contained mutations of KRAS, PIK3CA and NRAS (54.5, 58.0 and 56.0 years, respectively) were lower than that of patients containing all-wild types of KRAS, BRAF, PIK3CA and NRAS (median age, 64.0 years)." (PMID 24774510, 2014). "This initiative has led to the discovery of some key molecules and pathways including the vascular endothelial growth factor (VEGF) in tumor angiogenesis and the epidermal growth factor receptor (EGFR) with the therapy guiding KRAS/NRAS mutations." (PMID 25261368, 2014). "That is, one patient had a primary tumor that displayed BRAFV600E expression whereas the paired metastasis contained solely BRAF wild-type tumor cells, but harbored a NRAS mutation." (PMID 25526463, 2014). "Mutations were detected in 72 (31.9%) tumours for KRAS, in 6 (2.65%) for BRAF, in 7 (3.1%) for NRAS and in 37 (16.4%) for PIK3CA." (PMID 23374602, 2013). "We evaluated the assay in 6 different tumor types procured from commercial sources for the assay validation and compared our KBN-SNPE (KRAS, BRAF, NRAS Single Nucleotide Primer Extension) mutation assay results to Sanger sequencing and NGS." (PMID 23991070, 2013). "In half of the discrepant cases, we found a wild-type primary tumor and a mutated metastasis (78% BRAF and 22% NRAS)." (PMID 23987572, 2013). "Tumour DNA was pyrosequenced for KRASc.146, BRAF, NRAS, and PIK3CA mutations, and predefined molecular subgroups were analysed for interaction with the effect of panitumumab." (PMID 23725851, 2013). "The two tumours which were found to harbor mutations in the BRAF and NRAS gene also presented the ATF1-EWS fusion gene and were considered atypical." (PMID 22693489, 2012). "Patient with NRAS, KIT, and GNAQ mutations were also enrolled on specific trials directed at their tumor mutation status." (PMID 22536370, 2012). "The results revealed that 35 of our 68 tumor samples contained a BRAFV600 mutation, and 13 of the 68 samples contained an NRAS mutation." (PMID 22912864, 2012). "BRAF, NRAS and MET mutations were detected in 5 (50%), 3 (30%) and 1 (10%) of 10 FFPE tumor specimens, respectively, and 3 (20%), 2 (13.3%) and 2 (13.3%) of 15 cpDNA samples, respectively." (PMID 23144797, 2012). "In conclusion, we studied the prevalence of PIK3CA, RAS (KRAS, NRAS), and BRAF mutations in diverse tumor samples and identified a high frequency of coexisting PIK3CA and BRAF or RAS mutations." (PMID 21829508, 2011). "BRAF-wild-type clones present in primary tumours and metastases are likely to contain mutations or copy number alterations affecting genes other than BRAF, such as NRAS, KIT, cyclin D1, PTEN and CDKN2A." (PMID 21224857, 2011).
tumor (continued). "This can be achieved by either targeting both BRAF and CRAF or BRAF and PIK3CA simultaneously in NRAS mutant tumor cells." (PMID 19492075, 2009). "Our data shows that effective targeting of mutant NRAS driven tumor requires sustained reduction in pAKT and pERK." (PMID 19492075, 2009). "In in vivo tumor growth studies, tumors carrying shRNAs that target NRAS alone, or combinations of BRAF and CRAF, or BRAF and PIK3CA, showed a significant delay in tumor growth compared to the corresponding sucrose controls." (PMID 19492075, 2009). "To address the mechanism by which loss of RAS (KRAS in HCT116 and NRAS in IPC298) reduced cellular proliferation and delayed tumor growth, we analyzed cell cycle progression and apoptosis induction in these cells following dox treatment." (PMID 19492075, 2009). "In ALM, where canonical oncogenic mutations such as BRAF V600E and NRAS Q61 are less frequent, EZH2-driven epigenetic mechanisms may play an even more dominant role in tumor initiation and progression." (PMID 42220432, 2026). "Somatic mutations in KRAS, NRAS, BRAF, and the occurrence of microsatellite instability (MSI) were assessed using pyrosequencing and real-time PCR assays, respectively, on formalin-fixed, paraffin-embedded tumour samples." (PMID 42279292, 2026). "Overall, 40.5% of patients with available primary tumor tissue had a BRAF mutation in their tumor tissue (35.1% BRAFV600E, 2.7% BRAFV600R, BRAFV600K 2.7%), 18.9% of patients had a NRAS mutation (10.8% NRASQ61R, 8.1% NRASQ61K) and one patient (2.9%) had a KRAS mutation (KRASG12) in their tissue." (PMID 40652269, 2025). "MEK inhibitors have been studied as single medicines or in conjunction with PI3K/mTOR inhibitors for tumours with NRAS mutations, although data regarding their application in advanced CoM with NRAS mutation is lacking." (PMID 40831998, 2025). "Notably, whereas cells in the Notch1 TIC/tumor branch express ectopic NRAS at a level comparable with the OIS cluster, the Dlk1-type TIC/tumor branch shows a much lower NRAS expression." (PMID 40324881, 2025). "Another patient EP11, which was also not tested for NRAS in the clinical testing, tested positive for NRAS p.Gln61Lys in the whole tumour only, due to lack of coverage of this variant in other regions." (PMID 40302146, 2025). "In the EP group, 12 tumours had pathogenic mutations in key genes associated with response to anti‐EGFR therapy (1 × in BRAF + PTEN, 1 × in BRAF + PIK3CA, 2 × in BRAF, 3 × in PTEN, 2 × in NRAS, 1 × in KRAS, 1 × in HRAS and 1 × in PIK3CA)." (PMID 40302146, 2025). "Moreover, we observed that the combination of 5-Fu with cetuximab and Remodelin increased tumor regression in our xenograft mouse model of wild-type KRAS/NRAS/BRAF CRC." (PMID 39905540, 2025). "KRAS, NRAS, and BRAF hot-spot mutations statistical analysis at both nucleotide and protein changes offers a more nuanced perspective and granular picture underlying mutational processes driving tumor formation in different colon regions." (PMID 39857025, 2025). "Analyzing KRAS, NRAS, and BRAF hot-spot mutations at both the nucleotide and protein levels may offer insights into the mutational processes that influence tumor behavior, but functional studies are needed to validate these observations." (PMID 40075837, 2025). "These include a high tumor mutational burden (46 mutations per Mb), the presence of NRAS and NF1 mutations, and the absence of BRAF V600E mutations." (PMID 40125165, 2025). "The aim of this study was to quantify the expression levels of the immune checkpoint molecules TIM-3 and Gal-9 in CRC tissues and adjacent non-tumor tissue, and to investigate their associations with key oncogenic mutations, including KRAS, NRAS, BRAF, PIK3CA, and AKT1, as well as MSI status." (PMID 40724985, 2025). "However, a meta-analysis assessing the overall response rate (ORR) in NRAS mutant and NRAS wild-type patients indicated that NRAS mutant tumours have a better response rate to ICI." (PMID 40362630, 2025).